TSC1 (TSC complex subunit 1)
Diseases named in the same sentence as TSC1 in open-access papers (continued):
Sharing a sentence is not in itself a finding about the gene and the disease.
cognitive deficits (14 papers, 2009 to 2025). "Mouse models with mutations in Tsc1 or Tsc2 exhibit a phenotypic profile similar to human patients, including cognitive impairments." (PMID 39192595, 2024). "Its widespread use in the diagnosis of conditions including cognitive impairment has led to the detection of TSC1 and TSC2 variants in patients with less obvious clinical features and no family history of the disease." (PMID 38373162, 2024). "With respect to pathophysiological genetic studies on TSC-associated ASD symptoms, the following findings have been reported: an earlier report studied molecular changes associated with ASD-related symptoms such as social and cognitive deficits in the brain tissue of Tsc1+/− mice." (PMID 39852149, 2025). "TSC1 and TSC2 proteins form a complex that inhibits mTOR activity; therefore, deletion of these proteins causes hyperactive mTOR signaling, intellectual impairment, refractory epilepsy, intellectual impairment, and an autistic-like phenotype." (PMID 39845785, 2024). "Both of the TSC1 or TSC2 KO mice are embryonic lethal; however, mice harboring TSC1 or TSC2 heterozygous mutations display synaptic dysfunction and cognitive impairments." (PMID 29209173, 2017). "Thus, Tsc1 haploinsufficiency in Nkx2.1 inhibitory cells is sufficient to result in a subset of the hippocampus-related cognitive deficits observed in global Tsc mouse models." (PMID 32375878, 2020). "Finally, we observed correlated changes in hippocampal synaptic inhibition and cognitive impairments in mice with conditional Tsc1 haploinsufficiency in Nkx2.1 cells." (PMID 32375878, 2020). "Therefore, the downregulation of the tsc1 gene detected in As2O3-exposed larvae may be responsible for cognitive deficits observed in the current study." (PMID 36136458, 2022). "Because, other than in models carrying mutations in Tsc1, in models with Tsc2 aberrations, epilepsy is not found and not even predisposition to hyperexcitability is seen at early postnatal stages, this model allowed studying the occurrence of cognitive impairment independent of epileptic potential." (PMID 39192595, 2024).
cardiac rhabdomyoma (13 papers, 2017 to 2025). A well circumscribed benign tumor arising from cardiac muscle. "This case report presents an instance of fetal cardiac rhabdomyoma induced by a heterozygous TSC1 mutation, providing valuable insights for the early diagnosis and management of intrauterine fetal cardiac developmental abnormalities." (PMID 41142004, 2025). "The present case confirmed a de novo TSC1 mutation via whole-exome sequencing following induced labor, demonstrating that fetal cardiac rhabdomyoma can represent the initial manifestation of TSC even in the absence of a family history." (PMID 41142004, 2025). "In the present case, ultrasound findings suggested fetal cardiac rhabdomyoma, and when combined with the identification of a likely pathogenic TSC1 variant, a definitive diagnosis of Tuberous Sclerosis Complex type 1 (TSC1; OMIM: 191100) was established." (PMID 41142004, 2025). "As a specific fetal manifestation of TSC, with the pathogenesis of cardiac rhabdomyoma involving TSC1 mutations that induce aberrant activation of the mammalian target of rapamycin (mTOR) pathway, resulting in abnormal myocardial cell proliferation." (PMID 41142004, 2025). "Mutations in TSC1/TSC2 genes are often associated with cardiac rhabdomyomas in TSC." (PMID 38534508, 2024). "When cardiac rhabdomyoma is suggested by ultrasound, TSC1/TSC2 gene testing (e.g., whole-exome sequencing or targeted gene panels) is recommended, irrespective of family history." (PMID 41142004, 2025). "When fetal cardiac rhabdomyoma is identified via prenatal ultrasound, TSC1/TSC2 gene testing should be incorporated into routine evaluations to differentiate hereditary TSC from sporadic cardiac tumors." (PMID 41142004, 2025). "TSC results from mutations in TSC1 or TSC2 genes and leads to benign tumor formation in various organs, including cardiac rhabdomyomas and CNS lesions like cortical tubers." (PMID 40427120, 2025). "Cardiac rhabdomyomas were also found in TSC1 patients, but were approximately twice as common in TSC2 patients." (PMID 36232477, 2022). "The diameter of the largest cardiac rhabdomyoma in TSC1 and TSC2 patients was also investigated and ranged from 5 mm up to 34 mm, with the majority (22%) ranging from 10 to 15mm." (PMID 35440050, 2022). "The prevalence of DD/ID, renal AML, retinal hamartoma, and cardiac rhabdomyoma was significantly higher in TSC2 than in TSC1 patients." (PMID 36232477, 2022). "Furthermore, SEGA, cardiac rhabdomyomas, and renal AML occurred more frequently in patients with TSC2 variants than patients with TSC1 variants." (PMID 37946245, 2023). "The prevalence of UF and cardiac rhabdomyoma was higher in TSC1 and TSC2 patients, respectively." (PMID 36232477, 2022). "Moreover, cardiac rhabdomyomas were more common in TSC2, and ungual fibroma (UF) was more common in TSC1 patients." (PMID 36232477, 2022).
facial angiofibroma (12 papers, 2010 to 2025). "In another study, children at age of two years with a TSC1 gene mutation had less hypomelanotic macules and facial angiofibromas than those with a TSC2 genetic alteration." (PMID 38658236, 2024). "Tuberous sclerosis complex (TSC) is a neurogenetic syndrome due to loss-of-function mutations in TSC2 or TSC1, characterized by tumors at multiple body sites, including facial angiofibroma (FAF)." (PMID 35358092, 2022). "Patients with TSC2 variants were identified at a younger age (p = 0.003) and showed more retinal hamartomas and facial angiofibromas compared with patients with TSC1 variants (age ≥ 3 years) (p = 0.027)." (PMID 32211034, 2020). "Patients with TSC2 variants were first diagnosed at a younger age (p = 0.003) and had more retinal hamartomas (p = 0.003) and facial angiofibromas (p = 0.027) (age ≥ 3 years) than individuals with TSC1 variants." (PMID 32211034, 2020). "Adenoma sebaceum is part of the classical triad of tuberous sclerosis (adenoma sebaceum, mental retardation and epilepsy), which is an autosomal dominant neurocutaneous disease resulting from the mutation of TSC-1 or TSC-2." (PMID 20525327, 2010). "TSC1 is an autosomal dominant condition associated with protean neural and extra-neural manifestations including learning disability, seizures, infantile spasms, hamartomatous lesions of the brain, facial angiofibroma, café-au-lait spots, subungual fibromata, hypothyroidism, and neoplasias." (PMID 39712145, 2024). "The mean grade of facial angiofibroma appears to be higher in patients with a TSC2 than TSC1 alteration." (PMID 38658236, 2024). "TSC-LAM occurs in the setting of tuberous sclerosis complex (TSC), a multisystem genetic disorder characterized by mutations in TSC1 and TSC2, and is associated with additional clinical features including shagreen patches, facial angiofibromas, and recurrent seizures." (PMID 40761985, 2025). "Compared with individuals with TSC1 pathogenic variants, individuals with TSC2 pathogenic variants were first diagnosed at a younger age (p = 0.003) and had more retinal hamartomas (p = 0.003) and facial angiofibromas (p = 0.027) (age ≥ 3 years)." (PMID 32211034, 2020). "In patients with vs. without facial angiofibroma, TSC2 mutation (38.9% vs. 34.8%) was more common than TSC1 mutation (12.3% vs. 18.1%), and the incidence rate of most of the other TSC-related manifestations was significantly higher in patients with facial angiofibroma." (PMID 36104799, 2022).
kidney cancer (12 papers, 2012 to 2024). Primary or metastatic malignant neoplasm involving the kidney. "In the case of our patient, the TSC1 gene mutation was identified through an incidental finding of unifocal, unilateral RCC as an adult with a strong family history of kidney cancer, likely all RCC." (PMID 38802873, 2024). "Previous studies have found that several genes, including VHL, PBRM1 and TSC1, played an important role in tumorigenesis of kidney cancer." (PMID 34193180, 2021). "The findings suggest that genes associated with kidney cancer, including VHL, MET, FH, FLCN, TSC1, TSC2, and SDH, are involved in metabolic pathways linked to oxygen and iron or nutrient sensing, thus characterizing kidney cancer as a cellular metabolic disease." (PMID 35873461, 2022). "Multiple genes linked with kidney cancer, including the VHL, MET, FLCN, fumarate hydratase, succinate dehydrogenase, TSC1, TSC2, and TFE3, were identified by genomic studies and have significantly altered the ways in which patients with kidney cancer are managed." (PMID 29254180, 2017). "However, Pten deletion does enhance polycystic kidney disease and progression of the kidney cancer phenotype and decreases the lifespan of Tsc1 mutant mice by over activating the mTORC1 pathway." (PMID 22916036, 2012). "Recently, several characteristic kidney cancer-related genes, including VHL, MET, FLCN, TSC1, TSC2, FH, and SDH, have been reported to affect the metabolic stress response." (PMID 33686951, 2021). "Previous studies have shown that seven known kidney cancer genes, VHL, MET, FLCN, TSC1, TSC2, FH, and SDH, are involved in pathways that respond to metabolic stress or nutrient stimulation, suggesting that kidney cancer is a disease of dysregulated cellular metabolism." (PMID 31649873, 2019). "Interestingly, kidney cancer has been suggested as a metabolic disease, many kidney cancer genes like VHL, MET and TSC1/2 are involved in metabolism-related pathways." (PMID 25408144, 2014).
glioma (11 papers, 2014 to 2025). A benign or malignant brain and spinal cord tumor that arises from glial cells (astrocytes, oligodendrocytes, ependymal cells). "Syndromic NF1 germline mutations, similar to syndromic TSC1/2 mutations, are associated with low-grade gliomas that nevertheless differ in morphological appearance, with NF1 usually associated with pilocytic astrocytoma, and TSC with SEGA." (PMID 31258848, 2019). "The lncRNA KB-1460A1.5 regulates TSC1 expression by sponging miR-130a-3p and participates in miR-130a-3p/TSC1/mTOR/YY1 feedback loop to inhibit glioma tumorigenesis." (PMID 38725030, 2024). "Two tumor suppressors in the PI3K-mTOR pathway altered in the majority of human gliomas, PI3K regulatory subunit pi3kr1 and the tsc1 repressor of mTOR, were decreased in expression level in the Tg(flk1:RFP)is18 tumors." (PMID 25485542, 2014).
hepatocellular carcinoma (11 papers, 2012 to 2025). A malignant tumor that arises from hepatocytes. "We retrieved the Cancer Genome Atlas–Liver Hepatocellular Carcinoma (TCGA-LIHC) dataset and analyzed the correlation between the c-MYC activation status and TSC1/2 mutation status in human HCC." (PMID 39325536, 2024). "We established human hepatoma Hep 3Bx and Hep G2x cell lines which stably express HBx to investigate the effects of HBx overexpression on IKKβ/TSC1/mTOR signaling." (PMID 22848663, 2012). "Through transcriptome sequencing of human hepatocellular carcinoma (HCC) samples, six genes—TSC1, TSC2, PABPC3, HIF1α, RB1CC1 (ATG17), and RPS6KA3 (RSK2)—were found to be associated with HBV infection." (PMID 33059752, 2020). "We found that HBx modulated IKKβ/TSC1/mTOR signaling and up-regulated cell proliferation and VEGF production in both unstimulated and TNF-α-stmulated hepatoma cells." (PMID 22848663, 2012). "We have provided evidence that HBx activates IKKβ, which leads to inactivation of TSC1 and activation of mTOR/S6K1 and to the production of angiogenesis factor VEGF-A in HBx expressing hepatoma cells and liver tissues of HBx transgenic mice." (PMID 22848663, 2012). "After a round of screening followed by repeat assessment using probes for each exon of TSC1 and TSC2, the osteosarcoma cell line CAL-72 showed homozygous deletion of exons 6 to 23 of TSC1; and the hepatocellular carcinoma cell line SNU-398 showed homozygous deletion of exons 10–41 of TSC2." (PMID 33891611, 2021). "Guri and colleagues reported that mice lacking Tsc1 and Pten specifically in the liver (termed L-dKO mice) exhibited concomitant activation of mTORC1 and mTORC2 signaling and displayed hepatosteatosis progressing to hepatocellular carcinoma (HCC)." (PMID 37511253, 2023). "The three TSC2 null liver carcinoma cell lines SNU-886, SNU-878, and SNU-398 were uniformly sensitive to GSK461364, a PLK1 inhibitor, while in contrast the TSC1 null cell lines PEER and CAL-72 were not sensitive at all with IC50 values ranging from 5 to 33 nM." (PMID 33891611, 2021).
lung cancer (10 papers, 2008 to 2023). A malignant neoplasm involving the lung. "Loss of TSC1 synergizes with KRAS mutation to enhance the development of lung cancer in mice." (PMID 34616731, 2021). "Tuberous sclerosis complex subunit 1 (TSC1) and 2 (TSC2) are frequently mutated in non–small cell lung cancer (NSCLC), however, their effects on antitumor immunity remained unexplored." (PMID 35119931, 2022). "Through in vitro and in vivo CRISPR screening in a KP lung cancer model, we identified Tsc1 and Tsc2 as regulators of antitumor immunity and sensitivity to ICB therapy." (PMID 35119931, 2022). "To confirm the findings of in vitro CRISPR screening, we transfected lung cancer cell lines with individual sgRNAs of Tsc1 or Tsc2." (PMID 35119931, 2022). "In lung cancer, TSC1 and TBC1D7 have been shown to function as oncoproteins, possibly reflecting mTORC1-independent functions such as TSC1-mediated activation of TGFβ-SMAD2/3 signaling." (PMID 32630372, 2020). "Three phenotypically related genetic syndromes and their lesions (LKB1, PTEN, and TSC1/2) are identified as frequently altered in lung cancer." (PMID 18728656, 2008). "The lesions responsible for the syndromes, LKB1, PTEN, and TSC1/2, are identified as frequently altered in lung cancer, suggesting that they comprise elements of a common lung caner phenotype." (PMID 18728656, 2008). "We observed mutations in several important pan-cancer drivers not normally associated with lung cancer, including TSC1 in LUAD1 and LUSC5, and WT1 in LUAD6 and LUAD12." (PMID 30348992, 2019). "Notably, LOH for the TSC1 or TSC2 locus has been described in 22% of 86 human lung cancer specimens." (PMID 24593867, 2014). "TSC1 and TSC2 are also potent regulators of the expression of a transmembrane protein named Programmed cell death ligand 1 (PD-L1), a target of inhibitors in non–small cell lung cancer treatment." (PMID 35887000, 2022).
Obesity (10 papers, 2012 to 2023). Accumulation of substantial excess body fat. "It is possibly suggested that the hypothalamic Tsc1-mTOR signaling pathway plays a regulatory role in the obesity susceptibility of rats." (PMID 33532487, 2020). "We have now shown that rs1076160 (A/G) of TSC1 was related to obesity, with the minor G allele being protective against this condition." (PMID 28445147, 2017). "It is suggested that the methylation level of Tsc1 gene promoter in the hypothalamus may be the epigenetic mechanism regulating the differentiation of obesity susceptibility in rats." (PMID 33532487, 2020). "Our study suggests that the hypothalamic Tsc1-mTOR signaling pathway may play an important role in obesity susceptibility of rats, but the precise mechanism underlying this phenomenon is not yet clear." (PMID 33532487, 2020). "Therefore, we aim to investigate the methylation of the Tsc1-mTOR signaling pathway in regulation of obesity susceptibility." (PMID 33532487, 2020). "The association of TSC1 with obesity might be attributable to the effect of this gene on protein synthesis and cell growth, although the underlying mechanism remains unknown." (PMID 28445147, 2017). "Our previous experimental studies found that the promoter region of the Tsc1 gene in rat hypothalamus appeared to be at a high methylation state and its downstream mTOR gene expression was upregulated, thereby increasing appetite and food intake and finally causing obesity." (PMID 29853949, 2018). "Hypothalamic mTOR in Tsc1 knockout rats was activated; the appetite of rats increased and obesity occurred." (PMID 33532487, 2020). "Our investigation demonstrates that gene promoter methylation and expression of Tsc1 are closely related to the degree of obesity induced by high-fat diet; hypothalamic Tsc1 serves an important role in the maintenance of homeostasis of energy metabolism." (PMID 33532487, 2020). "The mTOR signaling pathway in the mouse hypothalamus with Tsc1 gene deletion is activated, and the food intake of mice is increased and obesity occurs." (PMID 33532487, 2020). "With an increase of the methylated modification of the Tsc1 gene promoter in the rat hypothalamus, the activity of downstream mTORC1 was enhanced, which further affected food intake and ultimately resulted in obesity." (PMID 29853949, 2018). "The treatment of obesity with EA, which was employed to reduce methylation Tsc1 and inhibit the activity of mTORC1, thereby controlling appetite-regulating factors (e.g., NPY, AgRP, and PoMC) and mitigating obesity." (PMID 29853949, 2018). "Tsc1 deletion mice developed hyperphagia, increased fat pads, and obesity and displayed increased activity of mTOR signaling." (PMID 29853949, 2018). "We also identified three genes (CROT, TSC1, RIN3) as new candidate susceptibility loci for obesity as well as three genes (ANKK1, ZNF804B, CSRNP3) and chromosome 17p11.2 as new candidate loci for MetS." (PMID 28445147, 2017). "The Tsc1-mTOR signaling pathway is often related to obesity, and epigenetic modification may lead to expression changes of obesity-related gene." (PMID 33532487, 2020). "Furthermore, we found that EA can reduce weight of obesity rat and, at the same time, the hypothalamic Tsc1 promoter demethylation and inhibition of the activity of mTORC1 occurred." (PMID 29853949, 2018). "Our study could shed light on the potential pathway where EA exerts effects on the mechanism of EA treatment for obesity through the hypothalamic Tsc1 promoter demethylation and inhibition of the activity of mTORC1 signaling pathway." (PMID 29853949, 2018). "In addition, single nucleotide polymorphisms in three genes (CROT, TSC1, RIN3) and at four loci (ANKK1, ZNF804B, CSRNP3, 17p11.2) were implicated as candidate determinants of obesity and metabolic syndrome, respectively." (PMID 28445147, 2017).